SERTAD2 (SERTA domain containing 2)
Description:
Acts at E2F-responsive promoters as coregulator to integrate signals provided by PHD- and/or bromodomain-containing transcription factors. May act as coactivator as well as corepressor of E2F1-TFDP1 and E2F4-TFDP1 complexes on E2F consensus binding sites, which would activate or inhibit E2F-target genes expression. Modulates fat storage by down-regulating the expression of key genes involved in adipocyte lipolysis, thermogenesis and oxidative metabolism.
Synonyms: TRIP-Br2; KIAA0127; TRIPBR2; Sei-2
Tractability: PROTAC: UniProt records ubiquitination sites on it.
Gene: Protein-coding gene on chromosome 2 (64,631,621 to 64,751,005, reverse strand). Ensembl gene ENSG00000179833.
Subcellular location: Nucleus; Cytoplasm
Subcellular location (Human Protein Atlas): Nucleoplasm; Cytosol
Gene Ontology:
Molecular function: protein binding; transcription coactivator activity
Biological process: negative regulation of cell growth; positive regulation of DNA-templated transcription
Cellular component: cytoplasm; cytosol; nucleoplasm; nucleus
Genetic constraint (gnomAD): Loss-of-function variants: 2 observed, 14.97 expected, observed/expected ratio (o/e) 0.13, 90% interval 0.054 to 0.42. The upper end of that interval is the gene's LOEUF score, 0.42, which puts it in group 1 of 6, group 1 being the genes least tolerant of losing a copy. Missense variants: 332 observed, 429.71 expected, observed/expected ratio (o/e) 0.77, 90% interval 0.7 to 0.85. Synonymous variants: 180 observed, 185.68 expected, observed/expected ratio (o/e) 0.97, 90% interval 0.86 to 1.1.
Homologues: Orthologues: chimpanzee SERTAD2 (99% identical), macaque SERTAD2 (96% identical), rat Sertad2 (87% identical), mouse Sertad2 (86% identical), rabbit SERTAD2 (86% identical), pig SERTAD2 (83% identical), tropical clawed frog sertad2 (77% identical), zebrafish sertad2b (62% identical), Drosophila melanogaster tara (25% identical). Paralogues in human: CDCA4 (23% identical).
Diseases named in the same sentence as SERTAD2 in open-access papers:
SERTAD2 is named in the same sentence as 16 diseases in open-access papers, as found by Europe PMC text mining. Sharing a sentence is not in itself a finding about the gene and the disease. The quoted sentences say what the papers report.
Obesity (4 papers, 2016 to 2020). Accumulation of substantial excess body fat. "Knockout of the SERTAD2 gene in mice prevents diet-induced obesity, insulin resistance and inflammatory responses in visceral fat." (PMID 30241500, 2018).
lung carcinoma (2 papers, 2022 to 2023). "The central member of the family of TLS polymerases (REV1) upregulates SERTAD2 expressions in a Rad18-dependent manner, thereby enhancing lung cancer development." (PMID 37396042, 2023). "In our follow-up experiments, SERTAD2 silencing was confirmed to inhibit the proliferation of lung cancer cells through colony formation and EdU incorporation assays." (PMID 35115490, 2022). "We found that knockdown of REV1 or SERTAD2 markedly suppressed the proliferation of lung cancer cells." (PMID 35115490, 2022). "In REV1-silenced lung cancer cells, the expression level of SERTAD2 was significantly reduced, and the expression levels of Rad18, mUb-PCNA and RPA32 were also reduced to varying degrees." (PMID 35115490, 2022). "SERTAD2 partially reversed the decrease in proliferation induced by REV1 silencing in lung cancer cells." (PMID 35115490, 2022). "We explored the expression of SERTAD2 by using TCGA, UALCAN and HPA database and found that SERTAD2 was highly expressed in lung cancer compared with paracancerous tissues, indicating that SERTAD2 may be an oncoprotein in lung cancer." (PMID 35115490, 2022). "Furthermore, overexpression of SERTAD2 partially reversed the suppression of lung cancer cell proliferation induced by silencing of Rad18." (PMID 35115490, 2022). "In addition, overexpression of SERTAD2 partially restored the inhibitory effect of Rad18 silencing on the proliferation of lung cancer cells." (PMID 35115490, 2022). "REV1 promotes lung tumorigenesis by activating Rad18/SERTAD2 signaling axis in lung cancer cells." (PMID 35115490, 2022). "Subsequent rescue experiments confirmed our hypothesis that the regulatory effect of REV1 on the proliferation of lung cancer cells is partially dependent on SERTAD2." (PMID 35115490, 2022). "The expression of SERTAD2 was significantly downregulated in REV1-silenced A549 and H1299 lung cancer cells." (PMID 35115490, 2022). "Since TLS is abnormally activated in lung cancer and REV1 is the central member of the TLS polymerase family, we speculated that the regulatory effect of REV1 on SERTAD2 is related to the biological process of TLS." (PMID 35115490, 2022). "Considering these results collectively, we proposed that SERTAD2 is an oncogene in lung cancer and REV1 may promote lung tumorigenesis by regulating the expression of SERTAD2." (PMID 35115490, 2022).
pancreatic ductal adenocarcinoma (2 papers, 2023 to 2024). An infiltrating adenocarcinoma that arises from the epithelial cells of the pancreas. "In pancreatic ductal adenocarcinoma, ZNF185 and SERTAD2 are tumor immune targets, providing new ideas for treatment of tumor immune invasion." (PMID 37396042, 2023). "It was found that RTP4, SERTAD2, and SP110 were significantly expressed in all pancreatic cancer cells, including those of pancreatic ductal carcinoma, pancreatic adenocarcinoma and metastatic carcinoma, providing a reliable basis for subsequent elucidation of pancreatic cancer pathogenesis." (PMID 37396042, 2023).
breast carcinoma (1 paper, 2021). "Many identified targets of miR-210 such as suppressor anaphase-promoting complex, cyclin-dependent kinase 10, SERTA Domain Containing 2 are involved in cell cycle regulation and correlate with aggressiveness of breast cancer." (PMID 34299605, 2021).
influenza (1 paper, 2025). An acute viral infection of the respiratory tract, occurring in isolated cases, in epidemics, or in pandemics; it is caused by serologically different strains of viruses (influenzaviruses) designated A, B, and C, has a 3-day incubation period, and usually lasts for 3 to 10 days. "The top-ranked genes for influenza classification included IFI27, ZFP36L1, TNC, SERTAD2, and AMPD3, several of which are known interferon-stimulated or antiviral response genes." (PMID 41020849, 2025).
lung adenocarcinoma (1 paper, 2022). A carcinoma that arises from the lung and is characterized by the presence of malignant glandular epithelial cells. "The GEPIA database prediction results showed positive correlations between the expression of Rad18, PCNA, RPA32 and that of SERTAD2 in lung adenocarcinoma; indeed, the correlation between Rad18 and SERTAD2 was the most significant (R = 0.46, P < 0.0001)." (PMID 35115490, 2022).
pancreatic cancer (1 paper, 2023). "SERTAD2 has been reported as an oncogene in pancreatic cancer." (PMID 37396042, 2023).
tumor (5 papers, 2013 to 2023). "To determine the role of SERTAD2 in REV1-mediated tumor promotion, we carried out a series of rescue experiments." (PMID 35115490, 2022).
cancer (4 papers, 2009 to 2024). A tumor composed of atypical neoplastic, often pleomorphic cells that invade other tissues. "Previous study identified SERTAD2 as a proto-oncogene and supports the potential for SERTAD2 as a novel prognostic marker and a chemotherapeutic drug target in human cancer." (PMID 35963640, 2022). "However, the mechanism of SERTAD2 in cancer development has not be fully elucidated." (PMID 35963640, 2022).
infection (1 paper, 2026). The state of being infected such as from the introduction of a foreign agent such as serum, vaccine, antigenic substance or organism. "Comprehensive characterization further identified Sertad2 as a key mediator promoting both nerve cell apoptosis and neuroinflammatory responses during infection." (PMID 42308359, 2026).
SERTAD2 also shares sentences with these, for which no sentence is quoted: Insulin resistance (2 papers); epithelial ovarian cancer (1); hyperlipidemia (1); metastatic carcinoma (1); osteosarcoma (1); pancreatic adenocarcinoma (1).